BPY2C (basic charge Y-linked 2C)
Synonyms: VCY2C
Gene: Protein-coding gene on chromosome Y (25,030,901 to 25,062,548, reverse strand). Ensembl gene ENSG00000185894.
Gene Ontology:
Molecular function: HECT domain binding; protein binding
Biological process: spermatogenesis; single fertilization
Cellular component: nucleus
Homologues: Paralogues in human: BPY2 (100% identical), BPY2B (100% identical).
Diseases named in the same sentence as BPY2C in open-access papers:
BPY2C is named in the same sentence as 2 diseases in open-access papers, as found by Europe PMC text mining. Sharing a sentence is not in itself a finding about the gene and the disease. The quoted sentences say what the papers report.
hepatocellular carcinoma (1 paper, 2024). A malignant tumor that arises from hepatocytes. "while AC006262.5 functions as an oncogene in hepatocellular carcinoma via the miR-7855-5p-BPY2C axis." (PMID 39600633, 2024).
BPY2C also shares sentences with these, for which no sentence is quoted: Azoospermia (1 paper).